TRIM28 (tripartite motif containing 28)
Diseases named in the same sentence as TRIM28 in open-access papers (continued):
Sharing a sentence is not in itself a finding about the gene and the disease.
tumor (continued). "Similarly, in the TRIM28-mutant tumours (with less statistical power) 80 probes showed significantly higher expression than non-mutant tumours, whereas 19 probes showed lower expression." (PMID 29912901, 2018). "In contrast to in vitro data, we observed a significant inhibition of tumor growth in vivo in MDA-MB-231 cells (95-98% CD44+/CD24−/low; relatively high level of OCT3/4) in contrast to MCF-7 or T-47D cells (1-10% CD44+/CD24−/low; relatively low level of OCT3/4) upon TRIM28 knockdown." (PMID 27845900, 2017). "Collectively, this study identifies XAF1 as a novel antagonist of TRIM28 and the presence of mutual antagonism between XAF1 and TRIM28, raising the possibility that the restoration of balanced XAF1-TRIM28 interplay could be an attractive avenue for the therapeutic intervention of tumor progression." (PMID 39532800, 2024). "Only for five genes, namely KAT2A, SMARCA4, BAZ1A, ATAD2 and TRIM28, we observed consistently higher levels and for two genes—KAT2B and SMARCA2—lower levels, respectively, regardless of the tumor type." (PMID 35049055, 2022). "The first aim of our study was to compare the gene expression of TRIM28 in a cohort of 95 GB and 19 LGG tumour samples and non-cancerous brain samples, as well as in primary patient-isolated differentiated GB cells vs. their GSC counterparts." (PMID 34500575, 2021). "In contrast, relative tumour growth in zebrafish embryo brain, determined as a change in mean fluorescence intensity of GBM xenografts, after addition of TRIM28 nanobody was not altered, implicating that a decrease in GB xenograft length is indeed a consequence of impaired cell invasion." (PMID 34500575, 2021).
infection (27 papers, 2011 to 2025). The state of being infected such as from the introduction of a foreign agent such as serum, vaccine, antigenic substance or organism. "These infections were followed by a subsequent 10 hour super-infection with IAV (MOI of 5 PFU/cell) to allow for infection-triggered loss of SUMO-modified TRIM28." (PMID 40920817, 2025). "A striking observation that came from re-analysis of influenza virus-triggered changes to the host SUMOylated sub-proteome is related to the loss of SUMOylated TRIM28 during infection." (PMID 33806893, 2021). "These combined analyses suggest that IAV-triggered loss of SUMOylated TRIM28 causes derepression of ERVs during infection." (PMID 31391303, 2019). "By combining genetics, transcriptomics, and classical virology, we report that infection-triggered loss of SUMOylated TRIM28 constitutes a previously unrecognized mechanism for the cell to mount innate immune defenses." (PMID 31391303, 2019). "Furthermore, pre-infection with Parainfluenza virus type 2, which encodes a V protein that efficiently engages with TRIM28, limits subsequent IAV-triggered loss of SUMO-modified TRIM28 and upregulation of HERVK14C RNA." (PMID 40920817, 2025). "Furthermore, pre-infection with PIV2 (or sole expression of its V protein that efficiently engages with TRIM28) limited subsequent IAV-triggered loss of SUMO-modified TRIM28 and/or derepression of selected EREs." (PMID 40920817, 2025). "To this end, we sought to analyze differences in infection-triggered changes to TRIM28 between PIV2 (representing a virus encoding a V protein that engages efficiently with TRIM28) and PIV5 (representing a virus encoding a V protein that engages less efficiently with TRIM28)." (PMID 40920817, 2025). "We used this knockout and reconstitution system to understand the impact that infection-triggered loss of SUMOylated TRIM28 might have on IAV replication." (PMID 31391303, 2019). "Using NAC to scavenge reactive oxygen species (ROS) we could also exclude ROS as cause of TRIM28 S473 phosphorylation during SC35M infection." (PMID 30323812, 2018). "To overcome this, we therefore designed a strategy to assess whether pre-infection with a paramyxovirus encoding a V protein that engages efficiently with TRIM28 (PIV2) could limit subsequent IAV infection-induced loss of SUMO-modified TRIM28 and derepression of EREs." (PMID 40920817, 2025). "While several known functions of V are thought to occur in the cytoplasm, there is extensive infection- and transfection- based evidence to indicate that many V proteins can be found in both the cytoplasm and nucleus, where TRIM28 primarily resides." (PMID 40920817, 2025). "While V proteins are well-established as antagonists of canonical cytoplasmic IFN signaling pathways, our new findings raise the possibility that V proteins also engage TRIM28 to suppress infection-triggered ERE-driven antiviral mechanisms." (PMID 40920817, 2025). "Here, we demonstrate that multiple paramyxovirus V proteins can complex with TRIM28, both in transient overexpression- and infection- based co-immunoprecipitation assays." (PMID 40920817, 2025). "Furthermore, pre-infection of cells with a paramyxovirus expressing a V protein that efficiently engages TRIM28 was able to partially inhibit subsequent IAV-induced loss of SUMO-modified TRIM28, as well as limit IAV-induced upregulation of a TRIM28-dependent ERE transcript." (PMID 40920817, 2025). "To further decipher how Smarcad1 depletion disrupts retroviral repression, we first applied ChIP using a Trim28 antibody to WT and Smarcad1 KD cells 2 and 7 days after infection." (PMID 38468276, 2024). "Beyond only reacting to active infections, TRIM28 plays a critical role in keeping some viruses in their latent state, which stops reactivation and the subsequent spread of disease." (PMID 39534556, 2024).
infection (continued). "Infection with KD shRNA led to a clear reduction in the protein level of TRIM28 when the cells were cultured in growth media and this effect was maintained after the cells had been induced to differentiate for 2 days." (PMID 39143258, 2024). "Overall, these data suggested that SUMOylation-deficient TRIM28 is unable to assist in the repression of some canonical innate immune response genes, the enhanced expression of which may act to prime cells for increased antiviral gene expression following infection." (PMID 31391303, 2019). "Normally, endogenous retroviruses are tightly repressed transcriptionally by host TRIM28, but infection triggers changes in the modification status of TRIM28 to alleviate repression." (PMID 31391303, 2019). "We confirmed that infection with IAV, IBV, and IAVΔNS1 leads to loss of posttranslationally modified TRIM28, and validated that this includes SUMOylated TRIM28." (PMID 31391303, 2019). "Elevated levels of IFN-β as well as the proinflammatory cytokines IL-6 and IL-8 were also observed during infection of TRIM28 KO cells with KAN-1." (PMID 30323812, 2018). "In summary, we have identified TRIM28 as a critical factor controlling excessive expression of type I IFNs as well as proinflammatory cytokines during infection with H5N1, H7N7, and H7N9 HPAIV." (PMID 30323812, 2018). "In summary, these results demonstrate that HPAIV of the H5N1, H7N7, and H7N9 subtypes induce phosphorylation of TRIM28 S473 at a late time point during infection." (PMID 30323812, 2018). "In conclusion, these data provide compelling evidence that TRIM28 S473 phosphorylation in response to PKR-dependent sensing of vRNA is mediated by the p38/MSK1-cascade during infection with HPAIV." (PMID 30323812, 2018). "We also confirmed our mass spectrometry data that RanGAP1 and PML are basally SUMOylated but largely do not change in modification status following IAV infection, whereas TRIM28 is highly deSUMOylated during infection." (PMID 26549460, 2015). "The ability of PIV2, but not PIV5, pre-infection to limit IAV-induced loss of SUMO2/3-modified TRIM28 correlates well with our observation that PIV2-V, but not PIV5-V, efficiently engages with TRIM28." (PMID 40920817, 2025). "We therefore hypothesized that V protein engagement with the TRIM28 PB during infection may act to disrupt regulated TRIM28 functions." (PMID 40920817, 2025). "In contrast, pre-infection with PIV5 did not provide substantial protection against IAV-induced loss of SUMO2/3-modified TRIM28." (PMID 40920817, 2025). "In this work, we used a different phospho-S824 TRIM28 antibody than in earlier reports and studied later times post-infection, which may potentially explain this discrepancy." (PMID 40920817, 2025). "To gain precise insights into the SUMOylation status of TRIM28 during infections with PIV2, PIV5 and IAV, we used a SUMO2/3-specific antibody to immunoprecipitate SUMO2/3-modified proteins from total cell lysates and assessed the SUMO2/3-modification status of TRIM28 by western blot." (PMID 40920817, 2025). "Unlike IAV infection, PIV2 and PIV5 infections did not lead to loss of SUMO-modified TRIM28, despite all three infections inducing the stress-associated TRIM28 phosphorylation at S824 that has been linked to reduction in SUMO-modified TRIM28 levels." (PMID 40920817, 2025). "We therefore hypothesized that other types of viruses also express proteins that engage with TRIM28, but which might limit its function in infection-triggered ERE derepression and potentiation of immune activation." (PMID 40920817, 2025). "Furthermore, we aimed to compare these paramyxovirus infections to infection with IAV, given that IAV infection leads to loss of SUMO-modified TRIM28 and the consequent upregulation of ERE transcripts in infected cells." (PMID 40920817, 2025). "Therefore, XAF1 modifies chromatin structure to enhance antiviral immunity by targeting TRIM28 during infection." (PMID 39532800, 2024).
infection (continued). "A previous study showed that CMV could establish latency in hematopoietic stem cells (HSCs) resulting in lifelong infection, and that TRIM28, also known as KAP1, is responsible for switching off viral genes in stem cells to maintain latency." (PMID 39360678, 2024). "TRIM28 mRNA levels were significantly lower in both groups of patients versus the control group and in the severe group indicated further reduction in comparison to mild infection." (PMID 36192760, 2022). "The TRIM28 is a negative immune regulator moderating IFNs and cytokine expression during infection with highly pathogenic avian influenza virus (HPAIV)." (PMID 36192760, 2022). "The transient transfection could be regarded as a process mimicking PFV primary infection, and thus, the result suggested that Trim28 bound to the U3 and U5-PBS region in PFV LTR promoter but not the R region, at the early stage of PFV primary infection." (PMID 34903241, 2021). "Furthermore, a critical role of TRIM28 in lytic gene expression during the early primary infection of herpes virus 8 has been identified." (PMID 32967368, 2020). "Because infection with IAV has been reported to induce DDR, we examined whether infection with SC35M induces the same phosphorylation pattern on TRIM28 compared to UV-radiation, H2O2 or etoposide treatment." (PMID 30323812, 2018). "Importantly, inhibition of p38 MAPK and MSK1 led to reduced TRIM28 S473 phosphorylation during infection with the HPAIV KAN-1 and Anhui in primary HUVECs." (PMID 30323812, 2018). "Infection of TRIM28 KO cells with VSV-luc resulted in decreased viral replication." (PMID 30323812, 2018). "This suggests that the degree of human adaptation as well as the reported characteristic to induce hypercytokinemia and tissue damage in humans might be determinants for TRIM28 phosphorylation during infection." (PMID 30323812, 2018). "In summary, our data demonstrate that S473 phosphorylation is functionally linked to increased expression of IFN-β, IL-6, and IL-8 and support our hypothesis, that phosphorylation at S473 modulates the corepressor activity of TRIM28 during infection with HPAIV." (PMID 30323812, 2018). "Here, we demonstrate that paramyxoviruses engage TRIM28, maintaining it in its repressive, SUMO-modified form during infection." (PMID 40920817, 2025). "Comparing data collected 24 hours post-infection in each study, four phosphosites were upregulated at least two-fold in four of these studies: HSPB1/HSP27 S15, MATR3 S188, TRIM28/TIF1B/KAP1 S473, and SZRD1 S107." (PMID 37345956, 2023). "TRIM28 and TRIM33 are known to form a trimeric complex with TRIM24, which itself was found (above) to reduce in abundance in lytic infection." (PMID 37410772, 2023). "Four additional infection-induced proteolytic cleavage sites identified in BCAP31, LASP1, MISP, and TRIM28 were consistent with the sequence specificity of 3CLpro." (PMID 37240067, 2023). "When interrogating the Vis AD cell proteome for proteins involved in the “interferon signaling” pathway, we found seven proteins altered by infection with CoV-2(P.1), among which five were upregulated (i.e., IRF1, HLA-C, TPR, EIF4G1, and TRIM28)." (PMID 36175400, 2022). "In contrast, we found six proteins altered by infection with CoV-2(B), among which five were downregulated (i.e., STAT1, HLA-E, TPR, TRIM25, and TRIM28)." (PMID 36175400, 2022). "To determine if the ILK inhibitor suppresses TRIM28 phosphorylation and HSV-1 replication, we treated HSV-1-infected SN-K-SH cells with OSU-T315 after 1 hour of infection." (PMID 35350437, 2022). "Expectedly, in the very early stages of infection, proteins involved in translation, transcription and DNA condensation were upregulated, notably HIST1H1E, HNRNPL, PRRC2A and TRIM28." (PMID 31315557, 2019). "Here, we identified TRIM28 as a key immune regulator leading to increased IFN-β and proinflammatory cytokine levels during infection with HPAIV." (PMID 30323812, 2018).
infection (continued). "Here, PKR senses viral RNA at a late time point during infection with HPAIV and provokes TRIM28 S473 phosphorylation via p38 and MSK1 with the consequence of excessive production of IFN-β, IL-6 and IL-8." (PMID 30323812, 2018). "Here, we have identified the host factor and transcriptional corepressor Tripartite motif-containing 28 (TRIM28/KAP1/TIF1β) as a critical regulator of IFN-β, IFN-γ and cytokine expression during infection with HPAIV." (PMID 30323812, 2018). "Depletion of TRIM28 and CDC37 led to mitigated phosphorylation of IKKα/IKKβ within 30-120 min of infection." (PMID 29581850, 2018). "We further found that PCV2 infection did not influence the interaction of TRIM28 with pNPM1 compared with the mock infection, and the inhibition of the TRIM28 expression did not alter the PCV2 infection-induced pNPM1 SUMOylation level." (PMID 38394330, 2024). "In contrast, given the essential role of TRIM28/SETDB1 in innate and adaptive immune responses, its preserved expression may contribute to maintaining effective immune protection against infection." (PMID 36826024, 2023). "Therefore, the promotion of ACE2 expression due to NK cell function and decrease in TRIM28 raise the possibility of infection with SARS-CoV-2 in lung epithelial cells and intensify lung inflammation and infection." (PMID 36192760, 2022). "Furthermore, after 36 h of infection with two shRNA lentivirus targeting SETDB1 respectively, the cell morphology was changed, which is similar to that after deletion of TRIM28, and deletion of SETDB1 also decreased the level of C-circle in U2OS cells." (PMID 34330324, 2021). "In addition, they showed that loss of SUMOylated TRIM28 was independent of PRRs and interferon α, supporting what we have seen in the expression time courses where TEs become up-regulated very early or during infection before significant changes in antiviral response genes." (PMID 31964680, 2020). "Most importantly, loss of TRIM28 S473 phosphorylation by inhibition of p38 and MSK1 also resulted in decreased levels of IFN-β, IL-6, and IL-8 during infection with SC35M, which was not caused by an inhibition of viral replication." (PMID 30323812, 2018). "Treatment of A549 cells with the p38 inhibitor SB202190 at specific and non-toxic concentrations efficiently blocked TRIM28 S473 phosphorylation during SC35M infection demonstrating that p38 plays a major role in this process." (PMID 30323812, 2018). "Treatment of A549 cells with non-toxic concentrations of the inhibitors for ATM and Chk2 prior to stimulation with H2O2, etoposide or infection with SC35M clearly demonstrated that these kinases are not involved in IAV-mediated TRIM28 S473 phosphorylation." (PMID 30323812, 2018). "Infection with SC35M clearly demonstrated that TRIM28 S473 was still phosphorylated in cells lacking the RIG-I downstream effector MAVS, which supported the previous results obtained in RIG-I KO cells (lane 7)." (PMID 30323812, 2018). "This revealed that the host factor TRIM28 was increasingly phosphorylated at S473 during infection with KAN-1 and FPV but not with PR8." (PMID 30323812, 2018). "In contrast, host proteins such as TRIM28 and DPF2 also migrated slower than expected in TAP-SUMO-purified samples, although their abundance in these fractions decreased with infection, suggesting a decrease in their SUMOylation that correlated with the mass spectrometry and western blot analyses." (PMID 26549460, 2015). "However, our results showed that PCV2 infection did not significantly alter the expression levels of ARF and TRIM28 in PK-15 cells compared with the mock infection." (PMID 38394330, 2024). "However, seven days after infection, Trim28 enrichment increased significantly in WT ESCs but not in Smarcad1 KD cells." (PMID 38468276, 2024).
infection (continued). "As a regards TRIM28 is an E3 ligase, and had higher expression in patients with mild symptoms compared to severe cases, it may contribute to the downregulation of the major SARS-CoV-2 entry receptor and decreasing the severity of infection in mild group." (PMID 36192760, 2022). "We also confirmed that SUMO-modified TRIM28 is lost during IAV infection of primary-like diploid MRC-5 cells concomitant with ERVV-1 and ERVV-2 induction, suggesting widespread up-regulation of cellular TEs in primary human cells during infection, similar to that observed in A549 cells." (PMID 31391303, 2019). "Indeed, infection with VSV-luc demonstrated that reconstitution with TRIM28 S473E resulted in significantly decreased viral replication compared to cell expressing wildtype TRIM28 and TRIM28 S473A." (PMID 30323812, 2018). "Unlike the DNA damage-inducing agent etoposide, IAV failed to trigger TRIM28 phosphorylation at Ser824, and functional inhibition of either ATM kinase (using KU55933) or the proteasome (using MG132 or lactacystin) was unable to prevent loss of posttranslationally modified TRIM28 during infection." (PMID 31391303, 2019). "Given the negative impact of HERVs and the positive effects of TRIM28/SETDB1 on innate and adaptive immune responses, the downregulation of the former and the normal expression of the latter may contribute to preserving immune functions against infection." (PMID 36826024, 2023).
metabolic disorder (3 papers, 2010 to 2024). "This analysis revealed a robust anti-correlation, implying that the metabolic disorder triggered by Mof haploinsufficiency is distinct from the one found in Trim28+/D9 obese mice and therefore unique to MOF function." (PMID 34707105, 2021).